SORL1 (sortilin related receptor 1)
Diseases named in the same sentence as SORL1 in open-access papers (continued):
Sharing a sentence is not in itself a finding about the gene and the disease.
Obesity (6 papers, 2017 to 2025). Accumulation of substantial excess body fat. "Mice genetically deficient for SORLA are protected from diet-induced obesity because of enhanced thermogenesis in adipose tissue, providing an explanatory model for the association of SORL1 with obesity in the human population." (PMID 27832290, 2017). "Although the exact mode of action in adipose tissues as humoral factor or as sorting receptor still awaits further clarification, all current data support the significance of SORL1 as genetic risk factor of obesity in the human population." (PMID 27832290, 2017). "Genome-wide association studies not only confirmed the relevance of SORL1 as a genetic risk factor for sporadic AD but also revealed a surprising association of this locus with metabolic traits (e.g., obesity and waist circumference) in humans and mouse models." (PMID 27832290, 2017). "Similarly, upregulation of the expression of Sorl1, which encodes for the protein Sorla, has been related to reduced lipolytic activity in adipocytes, and GWAS analyses have associated Sorl1 with obesity in humans and in mouse models, suggesting its key role in metabolic diseases." (PMID 31405230, 2019). "In addition, loss of SORLA expression in mice with targeted Sorl1 disruption is protected from diet-induced obesity, suggesting a so far unknown function for this receptor in metabolic regulation." (PMID 27832290, 2017). "Strikingly, Sorl1-/- mice are protected from high-fat diet obesity due to increased browning of white adipose tissue (WAT), and hypermetabolism." (PMID 36397124, 2022).
dementia with Lewy bodies (5 papers, 2019 to 2024). "Initially, both common and rare SORL1 variants have been associated with AD, while recently, deleterious variants have been also detected in frontotemporal lobar degeneration (behavioral variant and primary progressive aphasia), and dementia with Lewy bodies (DLB)." (PMID 36553628, 2022). "Additionally, Lewy body disease (LBD) was frequently observed in SORL1 R953C carriers." (PMID 38244079, 2024).
bladder cancer (4 papers, 2019 to 2022). "All in all, we identified a novel genomic signature—SORL1 that was closely related to immune microenvironment and predicted favorable outcomes in bladder cancer by exploiting public database." (PMID 34976002, 2021). "Then we screened out an immune microenvironment-related gene—SORL1—whose expression is related to the prognosis of bladder cancer validated by various methods." (PMID 34976002, 2021). "Although we identified a PD-1/PD-L1 genomic signature, SORL1, with favorable prognostic value for bladder cancer patients and explored the possible mechanism, there are several limitations in this study." (PMID 34976002, 2021). "Finally, the effects of the SORL1 gene on immunotherapy among bladder cancer patients in the real world are unclear." (PMID 34976002, 2021). "The results of our study indicate that SORL1 is a protective factor in bladder cancer." (PMID 34976002, 2021). "Additional exploration on the prognostic signature—SORL1 which would be a predictive biomarker for bladder cancer need to be performed to see whether it is benefit for patients who were treated with ICI agents." (PMID 34976002, 2021). "This may explain why SORL1 is a protective factor against bladder cancer." (PMID 34976002, 2021). "To investigate the SORL1-related pathway signatures, we performed GSVA on the TCGA bladder cancer samples." (PMID 34976002, 2021).
familial Alzheimer disease (4 papers, 2017 to 2024). A degenerative disease of the brain that causes gradual loss of memory, judgment, and the ability to function socially. "Sortilin‐related receptor 1 (SorL1) deficiency is a genetic predisposition to familial Alzheimer’s disease (AD), but its pathology is poorly understood." (PMID 39225620, 2024). "SORL1 downregulation enhances the amyloidogenic process of APP and significantly increases the risk of sporadic Alzheimer′s disease (SAD) and familial Alzheimer′s disease (FAD)." (PMID 36551230, 2022).
neuroblastoma (4 papers, 2022 to 2025). Neuroblastoma (NB) is the most common solid, extracranial childhood tumor. "Given that SORL1, GFRA1/2, ERBB2, are poorly or not expressed in SH-SY5Y neuroblastoma cells according to the Human Protein Atlas (last accessed on 12 September 2023), we made no attempt to model this trophic pathogenesis cascade in vitro." (PMID 37830614, 2023).
schizophrenia (4 papers, 2011 to 2022). A major psychotic disorder characterized by abnormalities in the perception or expression of reality. "Pik3ca also interacts with Lrp8, a gene related to the onset of neuropsychiatric diseases, such as schizophrenia, Mapk8, a gene associated with reduced apoptosis in glioblastoma cells, and Sorl1, which is decreased in AD brains by regulating Aβ accumulation." (PMID 36614117, 2022). "Here we present a patient with AD and SORL1 mutations whose first-episode psychotic symptoms occurred before the age of 65 and who was initially misdiagnosed with schizophrenia." (PMID 32183776, 2020). "These include ANK3, SORL1 and a region of chromosome 6p containing several genes implicated in schizophrenia and bipolar disorder." (PMID 25897833, 2015).
cerebral amyloid angiopathy (3 papers, 2019 to 2024). "We also present for the first time a patient with the homozygous truncating variant c.364C>T (p.R122*) in SORL1, who also had severe cerebral amyloid angiopathy." (PMID 35457051, 2022). "There is one report of a SORL1 homozygous truncating variant (c.364C > T, p.R122*) that shows severe cerebral amyloid angiopathy in addition to AD neuropathology as well as a patient with a splicing variant (c.4519 + 5G > A) in which AD was confirmed by neuropathological studies." (PMID 38244079, 2024).
cognitive decline (3 papers, 2021 to 2023). "In contrast, the T allele in SORL1 rs3737529 was significantly associated with a later midpoint of cognitive decline." (PMID 34214049, 2021). "Additionally, the APOE gene and SORL1 rs3737529 were associated with the rate of cognitive decline." (PMID 34214049, 2021). "In our previous study involving a MONW animal model with longer exposure to an HFD, we identified Sorl1 and Syn1 as potential indicators of early cognitive decline in PBMCs." (PMID 38203399, 2023). "Genotyping of selected single-nucleotide polymorphisms in the APOE, ABCA7, SORL1, BIN1, GAB2, and CD33 genes was conducted, and a Bayesian hierarchical model was fitted to analyze the trajectories of cognitive decline among different genotypes." (PMID 34214049, 2021). "Additionally, the rate of cognitive decline was associated with the APOE ε4 allele and SORL1 rs3737529." (PMID 34214049, 2021). "The T allele in SORL1 rs3737529 seems to be protective against cognitive decline independent of APOE genotype." (PMID 34214049, 2021). "Among these high-risk genes, those dysregulated in more than one cell type, such as CNTNAP2 and SORL1, may represent potential targets to defer the onset of cognitive decline and neurodegenerative diseases in the elderly." (PMID 34052996, 2021). "Moreover, the rate of cognitive decline was associated with the APOE gene (posterior mean = 0.96, 95% CI: 0.39, 1.57) and SORL1 rs3737529 (posterior mean = 0.58, 95% CI: 0.05, 1.14)." (PMID 34214049, 2021). "In summary, APOE and SORL1 might be the most important genetic factors related to cognitive decline in Han Chinese population." (PMID 34214049, 2021). "Moreover, the rate of cognitive decline was associated with the APOE ε4 allele and SORL1 rs3737529." (PMID 34214049, 2021). "In our previous study, SORL1 rs1784933 and rs2298813 were associated with AD and MCI risk in the Han Chinese population in Taiwan, and in the present study, SORL1 rs3737529 was associated with the midpoint and the rate of cognitive decline in AD and MCI patients in Han Chinese population." (PMID 34214049, 2021).
hippocampal atrophy (3 papers, 2016 to 2023). "Particularly, further study remains to be performed to assess the possible influence of these variants on Tau-related pathology or on hippocampal atrophy as has been described for a subset of SORL1 mutants." (PMID 38132122, 2023).
Onset (3 papers, 2021 to 2024). The age group in which disease manifestations appear. "Mutations in the sorting receptor-encoding gene SORL1 cause autosomal-dominant Alzheimer’s disease, and SORL1 variants increase risk for late-onset AD." (PMID 34133918, 2021).
ankylosing spondylitis (2 papers, 2022 to 2023). An autoimmune chronic inflammatory disorder characterized by inflammation in the vertebral joints of the spine and sacroiliac joints. "Upregulated of ANXA3, SORL1, and neutrophils can be key factors in the progression of Ankylosing Spondylitis." (PMID 35464477, 2022). "Upregulated of ANXA3, SORL1, and neutrophils may be a key factor in the progression of Ankylosing spondylitis." (PMID 35464477, 2022).
Atrophy (2 papers, 2016 to 2022). Any weakening or degeneration, especially through lack of use. "In the replication study, we found that SORL1 genetic variations were more inclined to be associated with atrophy rate in MCI individuals." (PMID 27177090, 2016). "Thus, we are the first to identify a link between putaminal/pallidal atrophy and SORL1 polymorphisms in AD." (PMID 35992588, 2022). "In this case, the SORL1-related MRI atrophy is probable the downstream consequence of the Aβ abnormalities." (PMID 27177090, 2016). "The association of putaminal or pallidal atrophy with common variants of SORL1 has not been previously specified in AD patients." (PMID 35992588, 2022).
Brain atrophy (2 papers, 2016 to 2022). Partial or complete wasting (loss) of brain tissue that was once present. "In the present study, we explored the effect of SORL1 genotypes on AD-related brain atrophy." (PMID 27177090, 2016).
diabetes (2 papers, 2022 to 2023). "SORL1 has previously been implicated in diabetes, providing an interesting direction for future studies comparing the incidence of diabetes and AD." (PMID 34370162, 2022).
glioma (2 papers, 2022 to 2024). A benign or malignant brain and spinal cord tumor that arises from glial cells (astrocytes, oligodendrocytes, ependymal cells). "Twenty days after GL261 glioma cells implantation, Sorl1 expression in GAMs (CD11b+ cells) isolated from brain tumors increased more than three times compared to the control cells." (PMID 38499808, 2024). "In this context, targeting SORL1 expression in GAMs or the interaction between SorLA and TNFα emerges as an exciting strategy for future pharmacological interventions in glioma." (PMID 38499808, 2024). "Moreover, in glioma patients, SORL1 expression levels in GAMs were related to their transcription profiles." (PMID 38499808, 2024). "Induction of Sorl1 expression in GAMs was recapitulated in a murine model of glioma." (PMID 38499808, 2024). "In line with our hypothesis, Sorl1 expression increased in the presence of glioma cells, while it dramatically decreased upon LPS treatment." (PMID 38499808, 2024). "Microglial expression of SORL1 was also noted in glioma patients’ brains." (PMID 38499808, 2024). "Distinct changes in microglial Sorl1 expression seen upon activation by LPS and in the presence of glioma cells suggested that SorLA might be an active player in shaping functional properties of microglia." (PMID 38499808, 2024).
ischemic stroke (2 papers, 2007 to 2023). A stroke disorder caused by obstruction of blood flow to the brain, due to thrombotic (local blood clot formation) or embolic (due to a blood clot or other material traveling from another site) event. "For example, prior associations of several of the candidate genes with related clinical disease phenotypes (for example, PDE4D with ischemic stroke, SORL1 with AD) have described allelic heterogeneity." (PMID 17903297, 2007).
memory impairment (2 papers, 2017 to 2024). "A SORL1 c.3050-2A > G variant was found in a patient with onset of AD at 54 years who belongs to a three-generational family with memory impairment, PED.27." (PMID 28595629, 2017).
mood disorder (2 papers, 2015 to 2025). A cognitive disorder a disturbance in which the person's mood is hypothesized to be the main underlying feature. "Another study concluded that the risk genes for AD associated with NPS include CD33 and EPHA1 for mood disorders related to AD and SORL1 (sortilin-related receptor 1 gene) for frontal symptoms." (PMID 40575244, 2025). "Closely associated SNPs rs1219407 and rs478903, which showed the strongest association with mood disorder in the prion+ vs prion− analysis, lie about 200 kb from the SORL1 gene." (PMID 25897833, 2015).
myelodysplastic neoplasm (2 papers, 2017 to 2024). "Our analysis predicted SORL1 as a candidate driver in multiple study groups, including myelodysplastic neoplasm (precursor of AML), B-cell precursor ALL, and a study group comprising T-cell non-Hodgkin lymphoma and T-cell acute lymphoblastic leukemia." (PMID 38769532, 2024).
age (1 paper, 2020). A temporal measurement of the time period elapsed since an identifiable point in the life cycle of an organism. "SORL1 encodes for the sortilin‐like receptor 1, a low‐density lipid receptor, whose downregulation has been implicated in age‐related Alzheimer disease." (PMID 32441410, 2020).
amyloidosis (1 paper, 2024). A disorder characterized by the localized or diffuse accumulation of amyloid protein in various anatomic sites. "MIC-M2 featured hub genes SORL1 and B2M, both implicated in a variety of AD-related processes such as trafficking of APP and resultant amyloidosis in AD." (PMID 38913039, 2024).
astrocytoma (1 paper, 2023). "Sortilin related receptor 1 (SorL1), a putative AD-linked gene was found downregulated in astrocytoma of high grade." (PMID 37335084, 2023).
bladder tumour (1 paper, 2021). "In summary, we herein described a novel PD1/PD-L1-associated signature, SORL1, that was associated with favourable outcomes among bladder tumour patients." (PMID 34976002, 2021).
Cerebral atrophy (1 paper, 2016). Atrophy (wasting, decrease in size of cells or tissue) affecting the cerebrum. "But we cannot exclude the other pathways by which SORL1 directly or indirectly act on the neural injury leading to the cerebral atrophy." (PMID 27177090, 2016).
Encephalopathy (1 paper, 2024). Encephalopathy is a term that means brain disease, damage, or malfunction. "Additionally, all generation II cases had TDP-43 inclusions in the amygdala and hippocampus, consistent with limbic-predominant age-related TDP-43 encephalopathy neuropathologic change (LATE-NC) stage 1 or 2 out of 3; TDP-43 inclusions were not seen in case I-2 (SORL1 variant negative)." (PMID 38244079, 2024).
Huntington disease (1 paper, 2013). Huntington disease (HD) is a rare neurodegenerative disorder of the central nervous system characterized by unwanted choreatic movements, behavioral and psychiatric disturbances and dementia. "In neurons, BDNF signaling increases Sorl1 transcription 10-fold whereas absence of BDNF activity in mouse models with genetic (Bdnf −/−) or disease-related loss of BDNF in the brain (Huntington’s disease, HD) results in impaired SORLA expression and activity." (PMID 23977241, 2013).
Hyperinsulinemia (1 paper, 2021). An increased concentration of insulin in the blood. "Metformin and hyperinsulinemia changed the expression of extracellular proteins (e.g. metformin: CTSL, EGFR, IL5, KLK3; insulin: IL4, IL15, PGC, SORL1)." (PMID 33690729, 2021).
Impaired glucose tolerance (1 paper, 2020). An abnormal resistance to glucose, i.e., a reduction in the ability to maintain glucose levels in the blood stream within normal limits following oral or intravenous administration of glucose. "Expression of Sorl1 and Rhpn1 is affected via a loss of miR-193b binding, which can be associated to increased fat mass and impaired glucose tolerance of NZO mice." (PMID 32350386, 2020).
ovarian carcinoma (1 paper, 2025). A malignant neoplasm originating from the surface ovarian epithelium. "We designed a screening experiment in which the control and SORL1 knockdown cell lines were treated with ten growth factors that were associated with chemoresistance in ovarian cancer." (PMID 39858026, 2025). "In our study, we further investigated the mechanisms underlying the potential role of SORL1 in promoting ovarian cancer cell growth and platinum resistance." (PMID 39858026, 2025). "In this study, we have identified that the upregulation of sortilin-related receptor 1 (SORL1) is associated with recurrent ovarian cancer and resistance to carboplatin." (PMID 39858026, 2025). "We focused on SORL1 in this study to provide more evidence on the role of SORL1 in ovarian cancer and carboplatin resistance since very limited knowledge related to SORL1 in ovarian cancer was developed." (PMID 39858026, 2025). "To better understand the function of SORL1 in ovarian cancer, we overexpressed SORL1 in ovarian cancer cell lines OVCAR8 and KRCH31 using transient transfection." (PMID 39858026, 2025). "Therapeutic agents targeting SORL1 and its related pathways have potential to overcome the platinum resistance of recurrent ovarian cancer." (PMID 39858026, 2025). "In ovarian cancer, one study reported that SORL1 can stabilize ATP-binding cassette subfamily member 1 (ABCB1, also known as multidrug resistance protein 1 or MDR1) to enhance resistance to cisplatin." (PMID 39858026, 2025). "We first examined the transcriptomic profiles of patients’ primary and recurrent ovarian cancers and identified the upregulation of SORL1 in recurrent tumors." (PMID 39858026, 2025). "The inhibition of SORL1 has the potential to overcome carboplatin resistance in ovarian cancer cells." (PMID 39858026, 2025). "Our results provide new mechanistic insights regarding the regulation of EGFR by SORL1 in ovarian cancer." (PMID 39858026, 2025). "The ovarian cancer cells overexpressing SORL1 showed increased proliferation in comparison to the control cells." (PMID 39858026, 2025). "We have provided in vitro and in vivo evidence to support the role of SORL1 in promoting carboplatin resistance of ovarian cancer cells." (PMID 39858026, 2025). "Even though the two cell lines (A2780 and SKOV3) used in this previous study do not represent the most common subtype of ovarian cancer, high-grade serous carcinoma, this study supports the potential role of SORL1 in contributing to chemoresistance in ovarian cancer." (PMID 39858026, 2025). "Moreover, when ovarian cancer cells were cultured in a 3D culture model, the single treatment of this SORL1-blocking antibody reduced the cell viability in a dose-dependent manner." (PMID 39858026, 2025). "We identified SORL1 as a gene promoting drug resistance in recurrent ovarian cancer." (PMID 39858026, 2025). "To date, we found only one study on SORL1 in ovarian cancer." (PMID 39858026, 2025). "In this study, we identified the upregulation of SORL1 in recurrent ovarian cancer and demonstrated SORL1’s role in promoting carboplatin resistance using a common ovarian cancer cell line, OVCAR8, and a patient-derived high-grade serous ovarian cancer cell line, KRCH31." (PMID 39858026, 2025). "Therefore, we decided to conduct mechanistic studies to better understand the role of SORL1 in regulating the growth of ovarian cancer cells and their response to chemotherapy." (PMID 39858026, 2025). "Our data also suggest that SORL1 interacts with EGFR and FGFR4, and their interactions are required to maintain the high levels of EGFR and FGFR4 proteins in ovarian cancer cells." (PMID 39858026, 2025). "This study has demonstrated the therapeutic potential of targeting the SORL1/FGFR4 pathway to improve the chemoresponse of patients with recurrent and/or resistant ovarian cancer." (PMID 39858026, 2025).